NLRC4 (NLR family CARD domain containing 4)
Diseases named in the same sentence as NLRC4 in open-access papers (continued):
Sharing a sentence is not in itself a finding about the gene and the disease.
Splenomegaly (2 papers, 2019 to 2025). Abnormal increased size of the spleen. "Moreover, recent evidence implicates the NLRC4 inflammasome in the pathogenesis of sterile inflammatory disorders as patients with NLRC4 gain-of-function mutations develop cytopenia, high ferritin levels, hemophagocytosis, and splenomegaly." (PMID 31520179, 2019). "Phenotypically, NLRC4 cKI mice presented splenomegaly and hepatomegaly." (PMID 41116055, 2025).
steatosis (2 papers, 2013 to 2022). Increased lipid within the cytoplasm of cells. "In contrast, the Nlrc4−/− mice had the lowest NAFLD activity scoring for steatosis after ethanol feeding compared to B6 and Nlrp3−/− mice." (PMID 24453428, 2013). "To confirm these conclusions in vitro, we cultured HDF cells and induced steatosis using sodium palmitate (10 mmol/L) and sodium oleate (10 mmol/L) for 24 h, and detected expression levels of ITGAM, ITGAL, and NLRC4 in cells." (PMID 36457728, 2022).
ulcerative colitis (2 papers, 2022 to 2023). An inflammatory bowel disease involving the mucosal surface of the large intestine and rectum. "Genome-wide association of NLRC4 (A160T) with ulcerative colitis was examined using data from the IBD exomes portal." (PMID 34783940, 2022). "In addition, a study showed that a higher risk of developing ulcerative colitis was associated with carriers with a gene variant of NLRC4." (PMID 37833958, 2023). "NLRC4 (A160T) can either cause recessively inherited autoinflammation and immune dysregulation, or function as a heterozygous risk factor for the development of ulcerative colitis." (PMID 34783940, 2022). "We now report the first homozygous mutation in NLRC4 (c.478G > A, p.A160T) causing autoinflammatory disease with immune dysregulation and find that heterozygous carriers in the general population are at increased risk of developing ulcerative colitis." (PMID 34783940, 2022). "As NLRC4 and NLRP3 have been demonstrated to be able to recruit the same inflammasome complex, the signaling of NLRC4 in ulcerative colitis may be similar to that of NLRP3." (PMID 37833958, 2023).
urticaria (2 papers, 2021 to 2022). A vascular reaction of the skin characterized by erythema and wheal formation due to localized increase of vascular permeability. "In this study, we identified a novel mutation in the NBD domain of NLRC4 in two patients, who presented just with recurrent urticaria and arthralgia." (PMID 34248956, 2021). "In summary, we identified a novel mutation in the NBD domain of NLRC4 in two patients with mild clinical phenotype including recurrent urticaria and arthralgia." (PMID 34248956, 2021). "In this study, we reported a novel mutation in NLRC4 in two Chinese patients, who manifested with recurrent urticaria and arthralgia." (PMID 34248956, 2021). "However, unlike the reported severe cases with mutations in the NBD domain, we herein identified a mutation in the NBD domain of NLRC4 in two patients, who just presented with recurrent urticaria and arthralgia." (PMID 34248956, 2021).
AA amyloidosis (1 paper, 2024). Secondary amyloidosis is a form of amyloidosis, that complicates chronic inflammatory disorders (mainly rheumatoid arthritis) and is characterized by the aggregation and deposition of amyloid fibrils composed of serum amyloid A protein, an acute phase reactant. "Here we report that ASC, the central component of the NLRP3, NLRC4 and AIM2 inflammasomes, coaggregates with SAA in tissues of patients with inflammation-associated AA amyloidosis." (PMID 39080493, 2024).
astrocytomas (1 paper, 2019). "Remarkably, the expression of NLRC4 was higher in the astrocytoma subtype than in oligodendroglioma and oligoastrocytoma subtypes and was associated with poor survival." (PMID 31133717, 2019).
autism (1 paper, 2022). Persistent deficits in social interaction and communication and interaction as well as a markedly restricted repertoire of activity and interest as well as repetitive patterns of behavior. "We found that Sgce and Plcg2 were the 2nd and 8th most downregulated transcripts, and Nlrc4 the 6th most upregulated transcript in microglia derived from control and LPS-treated mice upon an analysis of a subset of 148 autism and pediatric immune disorder genes." (PMID 35773312, 2022).
Azoospermia (1 paper, 2024). Absence of any measurable level of sperm,whereby spermatozoa cannot be observed even after centrifugation of the semen pellet. "The alignment of gene expression results from tissue and blood samples, coupled with ROC curve analysis, suggests that investigating AIM-2, NLRC-4/IPAF, and IL-18 could serve as three potential biomarkers for predicting and differentiating the causes of azoospermia." (PMID 39712014, 2024).
carotid atherosclerosis (1 paper, 2024). A thickening and loss of elasticity of the walls of carotid arteries that occur with formation of atherosclerotic plaques. "GSDMD, CASP1, NLRC4, AIM2, and IL18 were the key pyroptosis related genes, which might provide a new sight in the prevention of fatal strokes in advanced carotid atherosclerosis." (PMID 38167983, 2024).
Chagas disease (1 paper, 2023). A parasitic infection caused by Trypanosoma cruzi. "In this study, we investigated the activation of the NAIP/NLRC4 inflammasome in response to Trypanosoma cruzi, the protozoan parasite responsible for causing Chagas disease." (PMID 38124741, 2023). "In this study, we demonstrated a previously unknown role of NAIP/NLRC4 inflammasome in response to the T. cruzi infection, a protozoan parasite responsible for causing Chagas disease." (PMID 38124741, 2023).
chronic kidney disease (1 paper, 2017). Impairment of the renal function secondary to chronic kidney damage persisting for three or more months. "Among the NLR family members (NLRP1, NLRP2, NLRP3, NLRP6, NLRP12, and NLRC4), NLRP3 deficient mice had less tubular injury, inflammation, and renal fibrosis in chronic kidney disease (CKD)." (PMID 29100270, 2017).
developmental delay (1 paper, 2022).
encephalitis (1 paper, 2018). An acute inflammatory process affecting the brain parenchyma. "NLRC4 inflammasome is also activated in microglia or macrophages in case of meningitis or encephalitis." (PMID 30042341, 2018).
endometritis (1 paper, 2021). An acute or chronic, usually bacterial infectious process affecting the endometrium. "We found NLRC4−/− and AIM2−/−, NOD1−/−, NOD2−/−, and GBPchr3−/− mice developed severe endometritis at day 56 pi." (PMID 34526512, 2021).
endothelial dysfunction (1 paper, 2021). In vascular diseases, endothelial dysfunction is a systemic pathological state of the endothelium (the inner lining of blood vessels) and can be broadly defined as an imbalance between vasodilating and vasoconstricting substances produced by (or acting on) the endothelium. "Finally, it must be stressed that inflammasomes other than NLRP3, such as AIM2, NLRP1, NLRC4, and NLRP6, have not been thoroughly investigated so far in the context of the development of endothelial dysfunction and the impact on pathogenesis and progression of T2DM." (PMID 33546399, 2021).
experimental autoimmune encephalomyelitis (1 paper, 2022). An autoimmune demyelinating disease of the central nervous system that is produced experimentally in animals by the injection of homogenized brain or spinal cord in Freund's adjuvant. "LPC can also activate the NLRP3 and NLRC4 inflammasomes in macrophages, microglia and astrocytes, and NLRP3 is reported to be detrimental in experimental autoimmune encephalomyelitis." (PMID 35137954, 2022).
Failure to thrive (1 paper, 2025). Failure to thrive (FTT) refers to a child whose physical growth is substantially below the norm. "Notably, this phenotype mirrors the failure to thrive reported in patients harboring NLRC4 gain-of-function mutations." (PMID 41116055, 2025).
gastritis (1 paper, 2023). Inflammation of the stomach. "A study in 2023 on peptic ulcer disease found that the expression of NLRC4, NLRP12, IL-18 and IL-1β decreased significantly in patients of peptic ulcer disease compared with those of only H. pylori-associated gastritis." (PMID 37833958, 2023).
glioblastoma (1 paper, 2022). The most malignant astrocytic tumor (WHO grade IV). "Conversely, higher expression levels of GSDMB, GZMA, and GZMB were detected in T cells, whereas NLR4 and CASP5 showed specifically high expression levels in TAMs, and CASP5, GZMA, GZMB, and NLRC4 were barely detected in glioblastoma cells." (PMID 35990696, 2022).
glomerulonephritis (1 paper, 2021). A renal disorder characterized by damage in the glomeruli. "To determine the role of NLRC4 inflammasome in glomerulonephritis-HD patients, we analyzed the PBMCs by RT-qPCR for NLRC4 mRNA expression level." (PMID 34904012, 2021). "We also revealed that PBMCs isolated from glomerulonephritis-HD patients had elevated mRNA levels of NLRC4 compared to controls, suggesting the priming of NLRC4 inflammasome." (PMID 34904012, 2021). "However, no study has been investigated the role of NLRP3 and NLRC4 inflammasomes in inflammation associated with hemodialysis in patients suffered from glomerulonephritis." (PMID 34904012, 2021).
Granuloma (1 paper, 2020). A compact, organized collection of mature mononuclear phagocytes, which may be but is not necessarily accompanied by accessory features such as necrosis. "Considering the importance of IFN-γ-producer cells in typical TB granuloma formation, we therefore hypothesize that individuals with a defective NLRC4/IL18 axis are not able to effectively contain mycobacteria within granulomas, leading to eventual extra-pulmonary dissemination." (PMID 33193317, 2020).
hypertensive nephropathy (1 paper, 2024). Kidney damage that results from chronically elevated blood pressure; complications include glomerular damage resulting in proteinuria and hematuria. "The objectives in this work were to determine the role of NLRC4 in hypertensive nephropathy and compare the effects of MICT and HIIT on NLRC4." (PMID 39052650, 2024). "We also found that NLRC4 has the potential to become a new therapeutic target for hypertensive nephropathy." (PMID 39052650, 2024).
Hypoglycemia (1 paper, 2025). A decreased concentration of glucose in the blood. "In contrast, blood glucose levels were markedly reduced in NLRC4 KI mice, reflecting hypoglycemia." (PMID 41116055, 2025).
infarction (1 paper, 2025). A localised pathological necrosis of tissue resulting from obstruction of the blood supply usually by a thrombus, an embolus, or vascular torsion. "Post-infarction myocardial inflammation was characterized by increased Asc and Nlrp3 gene expression and caspase-1, IL-1β, and Nlrc4 protein expression." (PMID 40332346, 2025).
infertile (1 paper, 2024). "The ROC curve analysis indicated strong and significant predictive power of IL-18, AIM-2, and NLRC-4/IPAF gene expressions in differentiating between NOA vs. NS patients and NOA vs. OA infertile men." (PMID 39712014, 2024).
Insulin resistance (1 paper, 2025). Increased resistance towards insulin, that is, diminished effectiveness of insulin in reducing blood glucose levels. "The activation of NLRC4 inflammasome increases secretion of galectin-3 by myeloid cells through gasdermin D, thereby causing insulin resistance." (PMID 40433411, 2025). "Taken together, these findings suggest that inflammasomes, including NLRP3, AIM2, NLRP1, NLRP6 and NLRC4 inflammasomes are involved in the regulation of insulin resistance, pancreatic β-cell health and diabetes." (PMID 40433411, 2025).
Klebsiella Infections (1 paper, 2019). Infections with bacteria of the genus KLEBSIELLA. "However, there are contradictory results on the importance of NLRC4 to confer protection against Klebsiella infection." (PMID 30452654, 2019). "However, it is unlikely that this mechanism operates in the context of Klebsiella infections because the lack of NLRC4 does not affect Klebsiella-triggered pyroptosis." (PMID 30452654, 2019).
liver cirrhosis (1 paper, 2022). "Whether NLRC4 or Caspase-11 participates in liver cirrhosis needs further investigation." (PMID 35634294, 2022).
liver inflammation (1 paper, 2023). "The NLRC4 inflammasome has been shown to be crucial in bacterial infections in the liver, and NLRC4-mediated IL-1β release has been linked to liver inflammation." (PMID 36969233, 2023).
Majeed syndrome (1 paper, 2022). Majeed syndrome is a rare genetic multisystemic disorder characterized by the triad of chronic recurrent multifocal osteomyelitis, congenital dyserythropoietic anemia, and variable transient inflammatory dermatosis. "Monogenic SAIDs mediated by IL-1 include MKD, FMF, TRAPS, PAAND, PAPA, CAPS, DIRA, Majeed syndrome, NAIAD, NLRC4-MAS, PFIT, APLAID." (PMID 36253853, 2022).
mastitis (1 paper, 2018). Inflammation of breast tissue during lactation or postpartum due to an obstructed duct or infection. "Our findings identify NLRP3 and NLRC4 inflammasomes as potential targets for bovine mastitis therapy and could strengthen the development for other inflammasome-targeted therapies in E. coli-associated mastitis." (PMID 30087667, 2018).
metastatic cancer (1 paper, 2024). A carcinoma which has spread from the original site of growth to another anatomic site. "Therefore, epithelial NLRC4 expression is transmitting critical information between the epithelial innate and adaptive immune responses against metastatic cancer progression, leading to improved patient survival." (PMID 38652550, 2024).
periodontal diseases (1 paper, 2025). "This suggests that targeting the NLRC4-IL-1β pathway could be a potential therapeutic approach for managing periodontal diseases." (PMID 41009972, 2025).
Peritoneal Fibrosis (1 paper, 2019). Disorder characterized by a wide range of structural changes in PERITONEUM, resulting from fibrogenic or inflammatory processes. "In this regard, we observed no significant changes of these molecules in mice after MGO treatment; therefore, we assume that NLRP1, NLRC4, and AIM2 inflammasomes are less likely to be involved in MGO-induced peritoneal fibrosis." (PMID 31316105, 2019). "First, although we showed that NLRP3 deficiency significantly attenuates MGO-induced peritoneal fibrosis, we have not examined whether deficiency of other inflammasome-forming PRRs, such as NLRP1, NLRC4, and AIM2, could inhibit peritoneal fibrosis." (PMID 31316105, 2019).
plague (1 paper, 2015). Plague is a severe bacterial infection caused by the gram-negative bacterium Yersinia pestis. "To identify the host mediators of inflammasome activation during pneumonic plague, we examined IL-1β production and Y. pestis virulence within the lungs of NLRP3-/-, NLRC4-/- and wild-type mice." (PMID 25781467, 2015).
pneumococcal infection (1 paper, 2013). Infections with bacteria of the species streptococcus pneumoniae. "Furthermore, ASC is capable of binding and facilitating the function of several other inflammasomes (such as NLRC4 and IFI16), though the relevance of this during pneumococcal infection is not evident." (PMID 23902681, 2013).
Primary hemophagocytic lymphohistiocytosis (1 paper, 2021). "In severe cases, it is difficult to distinguish between AIFEC/NLRC4-MAS flares and primary hemophagocytic lymphohistiocytosis (HLH)." (PMID 34248956, 2021).
pulmonary diseases (1 paper, 2020). "The loss-of-function variant rs479333 in the NLRC4 gene (minor allele frequency, 49%; from ensembl.org) was less frequent in patients with extra-pulmonary TB than in patients with pulmonary disease." (PMID 33193317, 2020). "The role of NLRC4 in TB remains elusive because it has been poorly investigated in TB and pulmonary diseases." (PMID 33193317, 2020).
pulmonary TB (1 paper, 2020). "For the first time, we have shown that loss-of-function variants in NLRC4 significantly contribute to the development of extra-pulmonary TB." (PMID 33193317, 2020).
respiratory infection (1 paper, 2014). "Respiratory infection with Legionella pneumophila, another Gram-negative, flagellated, intracellular pathogen is also restricted by NLRC4 and this effect is dependent on the presence of flagellin." (PMID 25232720, 2014).
retinal degeneration (1 paper, 2020). Degeneration of the retina. "Overall these results suggest that NLRC4 does play a major role in mediating retinal cell death in retinal degeneration induced by photo-oxidative damage." (PMID 32041990, 2020). "We reasoned that inflammasome mediated-inflammation in retinal degenerations such as AMD may occur largely independently of NLRP3, NLRC4 or AIM2 sensor proteins." (PMID 32041990, 2020). "Finally, in addition to investigations into NLRP3, the role of NLRC4 and AIM2 inflammasome sensor proteins in retinal degenerations was examined." (PMID 32041990, 2020). "To identify whether inflammasome components in addition to CASP-1 might be responsible for the progression of retinal degenerations, we tested mice lacking NLRC4, AIM2 or ASC in our model of retinal degeneration." (PMID 32041990, 2020).
retinal ischemia (1 paper, 2020). A ischemic disease that involves the retina. "Given these novel findings, we have determined that IL-1β is a central factor enhancing CASP8-HIF-1α signaling to subsequently increase NLRP3/NLRP12/NLRC4 activation and to initiate pyroptosis during retinal ischemia." (PMID 32295623, 2020). "In the current study, we found that high IOP-induced retinal ischemia promoted the upregulation of NLRP12 and NLRC4." (PMID 32295623, 2020). "Together, these findings depict a novel function for NLRP12 in pyroptosis with regard to the pathogenesis of retinal ischemia and RGCs death, indicating that NLRP12 coordinates with NLRP3 and NLRC4 to exert both neuroinflammatory and pyroptotic effects under ischemic conditions." (PMID 32295623, 2020).
Rotavirus infection (1 paper, 2015). Infection with any of the rotaviruses. "Rotavirus infection was prevented and cured via the signaling pathway mediated by TLR5 and NOD-like receptor C4 (NLRC4), which led to production of IL-22 and IL-18 (mimicking the Th17-polarization)." (PMID 26213635, 2015).
septic shock (1 paper, 2021). Shock caused by infection; frequently caused by gram negative bacteria, although some cases have been caused by other bacteria, viruses, fungi, and protozoa; characterized by fever, chills, tachycardia, tachypnea, and hypotension. "The PPI net was produced via Cytoscape 3.6.0 software, wherein NLRC4 was discovered to be closely associated with several septic shock-related genes, signifying association with the occurrence of septic shock." (PMID 33406504, 2021).
Shock (1 paper, 2021). The state in which profound and widespread reduction of effective tissue perfusion leads first to reversible, and then if prolonged, to irreversible cellular injury. "Reduced levels of IL-1β, TNF-α and IL-6 were detected in the NLRC4-siRNA group, compared with the sham and NC-siRNA groups (all pCLP vs. NLRC4-siRNA < 0.001; pNC-siRNA vs. NLRC4-siRNA < 0.001), which suggested that NLRC4 gene silencing alleviated the inflammatory reaction induced by septic shock." (PMID 33406504, 2021).
skin cutaneous melanoma (1 paper, 2024). "Importantly, consistent with our finding showing a role for NLRC4 in protecting against metastatic progression in CRC, expression of NLRC4 (but not NLRP10) and type I IFN genes was associated with a significantly lower risk of metastasis in patients with skin cutaneous melanoma (SKCM)." (PMID 38652550, 2024).